ZEB1 (zinc finger E-box binding homeobox 1)
Diseases named in the same sentence as ZEB1 in open-access papers (continued):
Sharing a sentence is not in itself a finding about the gene and the disease.
tumor (continued). "We further investigate the effects of miR-652 and ZEB1 on tumor progression in vivo." (PMID 26498682, 2015). "For example, HIF-1α induces the gene expression of various EMT regulators, including Twist, Snail, and Zeb1, thereby promoting a more aggressive tumor phenotype, which confers on cancer cells the ability to invade basement membranes and metastasize to distant sites." (PMID 25821081, 2015). "Furthermore, the members of the miR-200 family together with miR-205 regulate the expression of target genes ZEB1 and ZEB2, which have been implicated to be involved in epithelial to mesenchymal transition and tumor progression." (PMID 25889518, 2015). "Functional involvement of LPA1 in ZEB1 expression in vivo was supported by the effect of a short treatment with Ki16425 (5 days) of animals with pre-established skeletal metastases that markedly reduced ZEB1 expression in the tumor metastasis." (PMID 26098771, 2015). "We then asked whether the tumor suppressor effects of miR-200b were mediated via the miR-200b-ZEB1/ 2-E-cadherin axis." (PMID 26334393, 2015). "Evidence indicates that uPa, c-Met and Zeb1 are important promoters of tumor phenotype." (PMID 26622315, 2015). "Here, we further elucidate how the ZEB1/miR-200 feedback loop controls invasion of tumor cells." (PMID 26334100, 2015). "In the present study we show that the EMT-inducer ZEB1 is not only driving the EMT program during the invasion process of tumor cells, but might be involved in bone metastasis formation as well." (PMID 25973542, 2015). "EMT is a process that exerts influence on many molecular, such as TGF-β, E-cadherin, N-cadherin Vimentin, ZEB-1, SMAD-2, SMAD-3, SMAD-7, GLI1 and GLI2; these molecules are closely associated with typical phenotype changes of EMT in tumor cell growth and metastasis." (PMID 25895132, 2015). "Moreover, eEF-2K regulates EMT, through modulation of the TCF8/ZEB1, Snail and claudins, further linking eEF-2K to malignant tumour progression." (PMID 25215932, 2014). "The efficacy mechanisms may involve in reinforcing immune responses, increasing expression of miR200c, E-cadherin and SMAD-7 and decreasing expression of TGF-β, ZEB1, Vimentin and N-cadherin in tumor tissues from the immunized mice." (PMID 24625224, 2014). "The TCF4 induced ZEB1 was also shown to be related to tumor invasiveness due to its effects in EMT." (PMID 25299301, 2014). "Treatment with the TGF-β signaling inhibitor A8301 as well as ZEB1 knockdown prevented the acquisition of mesenchymal marker expression and morphological changes, thus linking mesenchymal differentiation in GBM with enhanced tumor cell invasion through the TGF-β–ZEB1 axis." (PMID 25275602, 2014). "Multiple signaling pathways including TGFβ, Wnt and Notch working together with transcription factors such as Slug, Snail, Twist, Zeb1 and 2 suppress E-cadherin and induce EMT resulting in loss of cell-cell adhesion and increased tumor progression and migration." (PMID 25216513, 2014). "In addition, miR200c overexpression or ZEB1 knockdown is most likely to suppress tumor malignancy by enhancing E-cadherin expression and/or by inhibiting signals that suppress E-cadherin function." (PMID 24625224, 2014). "In addition to FN1 and SPARC, other well-established EMT-associated genes are also upregulated in these tumor samples following letrozole treatment including TWIST1, SNAI2, ZEB1, and ZEB2." (PMID 24944582, 2014). "Consistent with enhanced tumor-initiating properties, we observed that the transcription factors associated with cell pluripotency and EMT, i.e., Snail, Slug, Twist, Zeb-1, Nanog, and Oct-4 were significantly increased by RT-PCR in PC cells cocultured with Mo-MDSC." (PMID 24652403, 2014). "MiR-200c is able to suppress EMT through targeting of ZEB1/2 in some tumor cells." (PMID 24885194, 2014). "TGFβ-dependent activation of ZEB1 has been reported in other tumor types." (PMID 25275602, 2014).
tumor (continued). "ZEB1 is preferentially localised at the invasion front in tumour xenografts." (PMID 23818228, 2013). "ZEB1 expression in patient tumour samples is significantly enriched in the proliferative subclass, which appears in conflict with the lower proliferation of ZEB1-expressing cells in patient samples." (PMID 23818228, 2013). "Importantly, orthotopic grafts of shZEB1 cells showed a significantly decreased capacity for tumour initiation compared to control or ZEB1-expressing cells." (PMID 23818228, 2013). "Furthermore, GANT-61 inhibits PCSC-containing tumor growth, which is associated with upregulation of TRAIL-R1/DR4 and TRAIL-R2/DR5 expression and downregulation of Gli-1, Gli-2, Bcl-2, and ZEB1 expression in tumor samples obtained from nude mouse xenografts." (PMID 24325450, 2013). "However, other in vitro studies of TGF-β-induced EMT have identified miR-155, by RhoA targeting, and especially the miR-200 family in tumor metastasis, by targeting E-cadherin transcriptional repressors ZEB1/ZEB2, as EMT-promoting miRNAs." (PMID 23441172, 2013). "To validate whether ZEB1 promotes chemoresistance in vivo, we treated tumour-bearing animals grafted with either shZEB1 or shGFP cells with one cycle (five doses) of clinically relevant TMZ concentrations (20 mg/kg)." (PMID 23818228, 2013). "Since EMT has been associated with therapy resistance, we next tested whether ZEB1 affects response of tumour cells to the standard of care drug TMZ." (PMID 23818228, 2013). "ZEB1 is known to be associated with the EOC invasive and metastatic progression; ZEB1 is also known to be expressed in the EOC and be able to directly repress the epithelial marker E-cadherin to induce tumor cell invasive and metastatic progression." (PMID 23842108, 2013). "An assessment of OVOL to ZEB1 expression ratio may identify the trigger point for EMT-MET in various tumor cells." (PMID 24124593, 2013). "Among these tumors, 31% were also ZEB1 positive in the tumor compartment." (PMID 24216980, 2013). "The enrichment of EGFR expression in ZEB1 positive tumours suggests that tumour treatment may be more efficacious via EGFR inhibition in combination with TMZ treatment." (PMID 23818228, 2013). "All surviving tumor cells expressed cytoplasmic ZEB1 at this time point (ZEB1 24 h treated)." (PMID 24403226, 2013). "ZEB1 downregulates miR34a in a similar manner by directly repressing the miR34a-positive transactivating protein, ΔNp63, resulting in the acquisition of invasive tumor cell capabilities." (PMID 24283570, 2013). "We suggest that immunohistochemical evaluation of ZEB-1 expression in tumor nuclei may have clinical prognostic impact." (PMID 24304617, 2013). "Similarly, CDF decreased the mRNA levels of ZEB1, Vimentin, and Twist in the tumor sphere cells under hypoxic conditions." (PMID 23272057, 2012). "In the case of many carcinomas, EMT-inducing signals, such as HGF, EGF, PDGF, and TGF-β, emanate from the tumor-associated stroma and activate a series of EMT-inducing transcription factors, including Snail, Slug, zinc finger E-box binding homeobox 1 (ZEB1), Twist, Goosecoid, and FOXC2." (PMID 22479362, 2012). "We found that inactivation of miR-21 expression resulted in a significant decrease in the relative mRNA levels of EMT mesenchymal markers ZEB1 and Vimentin, and increased the relative mRNA level of epithelial marker E-cadherin in the tumor sphere cells under hypoxic conditions." (PMID 23272057, 2012). "In our study mesenchymal markers ZEB1 and vimentin were preferentially expressed in the tumor periphery, while the epithelial markers E-cadherin and β-catenin were reduced from cell junctions of some cells in the periphery, suggesting that these cells have undergone EMT." (PMID 23153292, 2012).
tumor (continued). "In agreement with this, nuclear β-catenin levels increased and a number of its target genes including cyclin D1, Zeb1 and vimentin, also known for their role in tumor proliferation and invasion, were induced upon exposure of naïve cells to CM from their senescent counterparts." (PMID 23272224, 2012). "Furthermore, ZEB1 can contribute to stemness maintenance thus enhancing the ability of tumor cells to both disseminate and to fuel the growth of metastases." (PMID 22916288, 2012). "Also, in PDAC tissue samples infiltrating neutrophils correlated with tumor cell expression of the EMT marker ZEB1." (PMID 23227088, 2012). "Our results could thus merely indicate that epithelial tumor cells initiate zeb1 and twist synthesis after being transformed to myoepithelial type cells." (PMID 21324165, 2011). "A Kaplan-Meier analysis comparing patients with Zeb1/δEF1 expression values either above or below the mean Zeb1/δEF1 expression value revealed that patients with tumours exhibiting lower Zeb1/δEF1 expression had a higher rate of disease recurrence (two-tailed Gehan-Breslow-Wilcoxon test, p = 0.004)." (PMID 19604397, 2009). "Numerous studies have demonstrated ZEB1 directly regulates the expression of Vimentin directly binding to the promoter region of Vimentin and inducing its transcription, resulting in the acquisition of a mesenchymal phenotype and enhancing tumor cell invasiveness." (PMID 41481650, 2026). "Furthermore, IRF-1 can inhibit downstream factors such as ZEB1, which may help suppress the epithelial-mesenchymal transition, migration, and invasion of tumor cells." (PMID 40909948, 2025). "In the tumor cells at metastatic locations, we detected meta-program IV (MAP2, GRIK2), a hallmark of neuron development, and meta-program I, the mesenchymal-neuroblast-like (MES-Nbt) state, which was enriched for genes related to the EMT such as ZEB1, ZEB2, and TEAD1." (PMID 41279557, 2025). "Both effects of ZEB1 ablation in fibroblasts, decreased barrier function and increased immune activation, point to a strong synergistic anti-tumor effect when combined with reovirus therapy, increasing both viral spread and enhancing reovirus-induced anti-tumor immunity." (PMID 41244268, 2025). "Our findings indicate that changes in ZEB1 and SNAI1 expression in PCa are associated with the induction of DEGs and downstream pathways that influence the TME and may facilitate immune evasion during tumor progression." (PMID 38672562, 2024). "Interestingly, ZEB1 showed a significant increase in tip cells of tumour samples, and the knockdown of ZEB1 significantly abrogated the tube formation rate of HUVECs in the presence of tumour cells." (PMID 38778448, 2024). "Moreover, ZEB1-mediated tumor progression was only prominent in immunocompetent murine models." (PMID 38191418, 2024). "However, the functional relevance of ZEB1 in CAFs and its effect on tumor progression is yet unknown." (PMID 38937629, 2024). "Thus, the formation of this LncRNA-SERB/ERβ/ZEB1 signaling axis may contribute to tumor metastasis and disease progression." (PMID 38641065, 2024). "Thus, a protein co-expressed with ZEB1 is likely to regulate the tumor cells through EMT process." (PMID 38954708, 2024). "Importantly, ZEB1 is not only expressed in the invasive front but also in the bulk, where it may sustain stem-like features and tumor-initiating properties." (PMID 38519642, 2024). "As a transcription factor, ZEB1 might drive tumor metastasis by regulating downstream lncRNAs." (PMID 38965605, 2024). "While several studies reported that ZEB1 tumor expression is also associated with immune tolerance including the accumulation of suppressive macrophages and CD8 T cell exhaustion, the underlying drivers of ZEB1 activation remain unclear." (PMID 38191418, 2024).
tumor (continued). "Also noteworthy, EMT-TFs may have opposing roles in a particular tumor type, such as melanoma, where ZEB1 promotes EMT programs with the help of TWIST1, while ZEB2 in cooperation with SNAI2/SLUG are inhibitors." (PMID 36754910, 2023). "At the molecular level, EMT transcription factors, including Snail, ZEB1, and Twist1, attract immunosuppressive cells through the production of chemokines or promote the expression of immunosuppressive checkpoint molecules, thus forming a tumor immunosuppressive microenvironment." (PMID 37926835, 2023). "Therefore, the deletion of Zeb1 in DC resulted in a decrease in both the number and effector function of CD8+ T cells in tumors, which was unlikely due to regulatory T (Treg) cells, as the numbers of tumor-infiltrating Treg cells in WT and Zeb1-dcKO mice were comparable." (PMID 37863917, 2023). "Interestingly, cancer cells in the mixed/hybrid E/M state exhibited prospective cancer stem cells (CSCs) properties suggesting that ZEB1 might be a determinant of stemness characteristics in tumor cells." (PMID 38139138, 2023). "Interestingly, a weak WNT5A up-regulation was observed in the M13HS-2 and -8 ZEB1-KO tumor hybrids." (PMID 38139138, 2023). "In addition, cell migration/invasion assay also showed that ZEB1 overexpression vector cotransfection in KYSE-30 cells could alleviate the effects of TRIM9 overexpression vector transfection on tumor cell migration and invasion." (PMID 37124931, 2023). "Similarly, only the M13HS-8 ZEB1-knock-out tumor hybrids showed a reduced invasion capacity." (PMID 38139138, 2023). "They showed that miR-200b-3p can target against zinc finger E-box-binding homeobox 1/2 (ZEB1/2), microfibril-associated glycoprotein 2 (MAGP2), mothers against decapentaplegic homolog 2 (SMAD2) and high mobility group box 3 (HMGB3), thereby inhibiting tumor growth, apoptosis and cellular mobility." (PMID 37705067, 2023). "Interestingly, the epithelial differentiation in OSCC metastases is associated with higher activity of the EMT-activator ZEB1, which was confirmed on protein level by detection of co-expression of ZEB1 and cornifin-B in individual tumor cells using immunofluorescence staining." (PMID 37076857, 2023). "However, in our analysis of human BCBM, we observed cancer cells that escaped from the tumor mass and invaded the brain parenchyma contained a typical mesenchymal profile of expressing Zeb1 and losing E-cadherin, but interestingly still expressing the epithelial marker Pankeratin." (PMID 35804890, 2022). "Overexpression of miR-200c significantly downregulates the expression of ZEB1 and vimentin, but upregulates E-cadherin expression, resulting in decreased colony formation, migration, and invasion, as well as a reduction in metastatic tumor cells in mouse lung xenografts." (PMID 35805066, 2022). "Moreover, ZEB1 may regulate CD8+ T cell-dependent tumor growth at least in part independently of MITF-mediated phenotype switching, since similar phenotypes were observed in MITFhigh and MITFlow backgrounds." (PMID 35432344, 2022). "Thus, by reforming the tumor microenvironment, ZEB1 is vital to tumor progression." (PMID 35454770, 2022). "Thus, understanding the regulation of ZEB1 in driving tumor progression and invasion could provide awareness of the biomolecular mechanisms through which cells acquire metastatic properties." (PMID 35454770, 2022). "Furthermore, ZEB1 promotes tumor growth, whereas ZEB2 reduces tumor aggressiveness in melanomas." (PMID 35805066, 2022). "The ZEB1 gene encodes the Zinc Finger E-Box Binding Homeobox 1 (ZEB1) protein, a zinc finger transcription factor that acts as a transcriptional repressor, represses E-cadherin promoter and induces the epithelial-to-mesenchymal transition (EMT), promoting tumor invasion and metastases." (PMID 35282432, 2022).
tumor (continued). "Zeb1 is also reported to inhibit the expression of stemness-repressing miRNAs in PDAC cells, suggesting this loss of heterogeneity may also be linked to a loss of CSC properties in the tumour." (PMID 36088504, 2022). "Indeed, some of these TFs such as SNAI1 and ZEB1 were shown to induce EMT in most of the tumor cell/tissue types tested, while few others such as GATA4, GATA6, PRRX1 etc. were found to promote EMT in certain cell/tissue types only, and even block the EMT process in others." (PMID 34708244, 2022). "Moreover, downregulation of ZEB1 may reduce the UM cell proliferation rate and tumor size and, thereby, delay the generation of cancer stem cells." (PMID 35404029, 2022). "Additionally, YAP1 could also form a transactivation complex with AP-1 and ZEB1 to activate predominantly tumor-promoting genes." (PMID 36210463, 2022). "Moreover, FTO silencing reduced mRNA levels of ZEB1 in SN-exo-cultured tumor cells." (PMID 36302751, 2022). "Interestingly, although EMT is linked to the escape from cellular senescence during tumor initiation, our study shows that senescent neutrophils can secret exosomes to induce EMT-related chemoresistance of BC cells, and this effect is dependent on ZEB1." (PMID 36302751, 2022). "In addition, we also identified Biochanin A as a novel inhibitor for the ZEB1/PD-L1 axis, which could inhibit tumor progression and immune escape." (PMID 35242187, 2022). "In GBM, miR-139-5p may suppress tumor cell invasion and migration via targeting ZEB1 and ZEB2." (PMID 34001135, 2021). "Therefore, the identified underlined mechanism by which ZEB1 is dynamically regulated during cancer progression may explain why ZEB1-manipulated tumor plasticity/heterogeneity drive tumor cells to therapy resistance and relapse." (PMID 34462429, 2021). "Moreover, TF ETS1 could activate target genes CXCR4 and ZEB1 to trigger metastasis mediated by downstream core signaling cascades through the suppression of tumor inhibitor, miRNA MIR497." (PMID 33802957, 2021). "We spontaneously want to know whether ZEB1-PFKM axis contributes to tumor progression." (PMID 33897890, 2021). "Interestingly, miR-128 also seems to target ZEB1 in a tumor-suppressive manner." (PMID 34884646, 2021). "Thus, Zeb1 acts as a tumor suppressor in MLL-AF9 and Meis1a/Hoxa9 AML LSCs." (PMID 33108352, 2021). "H19 facilitates the invasion of colon cancer cells via miR-200a sponging mechanism and consequential ZEB1/2 upregulation, while its overexpression results in upregulation of vimentin and downregulation of E-cadherin, and indicates a significant increase in tumor size in vivo." (PMID 35011635, 2021). "Besides, miR-409 could function as a tumor suppressor in several cancers by targeting zinc-finger E-box-binding homeobox-1 (ZEB1), E74-like factor 2 (ELF2), and GRB2-associated binding protein 1 (GAB1)." (PMID 34338153, 2021). "Besides, inhibition of ZNRD1‐AS1 attenuated tumor growth by miR‐194/ZEB1 axis in vivo." (PMID 32862492, 2020). "In particular, zinc finger E–box binding homeobox 1 (ZEB1) is a key nuclear factor that specifically binds to and represses the promotor region of E–cadherin, suggesting that a decreased expression of E–cadherin could occur in tumor cells." (PMID 33032610, 2020). "Moreover, ZEB1 overexpression was marginally significant when GC tumor size is concerned." (PMID 32153739, 2020). "Elevated expression of ZEB1 not only increases cell motility and invasiveness by downregulating epithelial markers and upregulating mesenchymal markers but also contributes stem cell-like features to tumor cells, providing resistance to various types of therapy." (PMID 32014049, 2020). "However, all tumor cells derived from PyMT;Zeb1cKO mice were fixed in an epithelial state, implying that Zeb1-enhanced plasticity of cancer cells represents ongoing transitions between an undifferentiated/(partial) mesenchymal and a differentiated/epithelial phenotype." (PMID 33046710, 2020).